SNRPD3 (small nuclear ribonucleoprotein D3 polypeptide)
Description:
Plays a role in pre-mRNA splicing as a core component of the spliceosomal U1, U2, U4 and U5 small nuclear ribonucleoproteins (snRNPs), the building blocks of the spliceosome. Component of both the pre-catalytic spliceosome B complex and activated spliceosome C complexes. As a component of the minor spliceosome, involved in the splicing of U12-type introns in pre-mRNAs. As part of the U7 snRNP it is involved in histone pre-mRNA 3'-end processing (By similarity).
Synonyms: Sm-D3; SMD3
Tractability: Small molecule: a structure with a bound ligand is known. PROTAC: ubiquitination databases record sites on it; its protein half-life has been measured.
Gene: Protein-coding gene on chromosome 22 (24,555,957 to 24,584,044, forward strand). Ensembl gene ENSG00000100028.
Subcellular location: Cytoplasm, cytosol; Nucleus
Subcellular location (Human Protein Atlas): Nucleoplasm; Cytosol; Nuclear bodies
Pathways (Reactome):
Metabolism of RNA: SLBP Dependent Processing of Replication-Dependent Histone Pre-mRNAs; SLBP independent Processing of Histone Pre-mRNAs; mRNA Polyadenylation; mRNA Splicing - Major Pathway; mRNA Splicing - Minor Pathway; snRNP Assembly
Disease: Dengue Virus-Host Interactions; SARS-CoV-2 modulates host translation machinery
Chromatin organization: CHD1 and CHD2 subfamily
Gene expression (Transcription): RNA Polymerase II Transcription Termination
Gene Ontology:
Molecular function: enzyme binding; protein binding; RNA binding; telomerase RNA binding; U7 snRNA binding; histone pre-mRNA DCP binding
Biological process: mRNA splicing, via spliceosome; protein methylation; spliceosomal snRNP assembly; 7-methylguanosine cap hypermethylation; negative regulation of mRNA splicing, via spliceosome; nuclear histone mRNA catabolic process; RNA splicing; spliceosomal complex assembly; spliceosomal tri-snRNP complex assembly; spliceosome conformational change to release U4 (or U4atac) and U1 (or U11); U2-type prespliceosome assembly; RNA processing
Cellular component: catalytic step 2 spliceosome; cytosol; methylosome; nuclear body; nucleoplasm; nucleus; pICln-Sm protein complex; post-mRNA release spliceosomal complex; post-spliceosomal complex; precatalytic spliceosome; SMN-Sm protein complex; spliceosomal complex; telomerase holoenzyme complex; U1 snRNP; U11/U12 snRNP; U12-type catalytic step 2 spliceosome; U12-type precatalytic spliceosome; U12-type spliceosomal complex; U2-type catalytic step 1 spliceosome; U2-type catalytic step 2 spliceosome; U2-type precatalytic spliceosome; U2-type spliceosomal complex; U4 snRNP; U4/U6 x U5 tri-snRNP complex; U7 snRNP; and 10 more
Genetic constraint (gnomAD): Loss-of-function variants: 0 observed, 15.08 expected, observed/expected ratio (o/e) 0, 90% interval 0 to 0.2. The upper end of that interval is the gene's LOEUF score, 0.2, which puts it in group 1 of 6, group 1 being the genes least tolerant of losing a copy. Missense variants: 73 observed, 173.4 expected, observed/expected ratio (o/e) 0.42, 90% interval 0.35 to 0.51. Synonymous variants: 66 observed, 61.38 expected, observed/expected ratio (o/e) 1.08, 90% interval 0.88 to 1.32.
Homologues: Orthologues: chimpanzee SNRPD3 (100% identical), guinea pig SNRPD3 (100% identical), macaque SNRPD3 (100% identical), mouse Snrpd3 (100% identical), rabbit SNRPD3 (100% identical), rat Snrpd3 (100% identical), tropical clawed frog snrpd3 (100% identical), zebrafish snrpd3l (98% identical), dog SNRPD3 (88% identical), Drosophila melanogaster SmD3 (77% identical), rat Snrpd3l1 (75% identical), Caenorhabditis elegans snr-1 (61% identical). Paralogues in human: LSM4 (32% identical), SNRPD1 (32% identical).
Diseases named in the same sentence as SNRPD3 in open-access papers:
SNRPD3 is named in the same sentence as 24 diseases in open-access papers, as found by Europe PMC text mining. Sharing a sentence is not in itself a finding about the gene and the disease. The quoted sentences say what the papers report.
breast carcinoma (5 papers, 2021 to 2025). "Recent studies have found that SNRPD2 and SNRPD3, as RNA splicing factors, can inhibit the proliferation of breast cancer cells and laryngeal squamous carcinoma cells and participate in the study of cell cycle-related mechanisms during early fracture." (PMID 36389112, 2022). "Moreover, several studies have shown that SNRPD3 expression is relevant to breast cancer and NSCLC." (PMID 35356432, 2022). "In addition, a study also found that SNRPD3 might be a novel breast cancer-related biomarker." (PMID 34976013, 2021).
lung carcinoma (3 papers, 2017 to 2025). "Similarly, we identified several splicing proteins, such as SNRPD2, SNRPG, SNRPD3, HNRNPM, HNRNPH3, and SRSF10, in human breast and lung cancer TuNEPs but not in NETs." (PMID 40751052, 2025).
COVID-19 (2 papers, 2022). A disease caused by infection with severe acute respiratory syndrome coronavirus 2. "Of note, we observed numerous DTU genes involved in RNA splicing, with 10 genes (e.g. HNRNPC, SNRPD3, QKI, and LUC7L2) increased major transcript usage and 18 genes (e.g. SNRNP48, NCBP1, CELF2, RALY, and PABPC1) decreased major transcript usage in the COVID-19 patients." (PMID 35421082, 2022).
anemia (1 paper, 2019). A reduction in the number of red blood cells, the amount of hemoglobin, and/or the volume of packed red blood cells. "We examined global transcriptome alterations following depletion of DNA replication checkpoint genes (Atr, Mcm4, Mcm5, and Mcm6), the Fanconi anemia gene (Fanca), mRNA processing genes (Snrpal and Snrpd3), and CMT genes (Sh3tc2 and Cmt4b2)." (PMID 31390555, 2019).
heart failure (1 paper, 2023). Inability of the heart to pump blood at an adequate rate to meet tissue metabolic requirements. "Dhx9, Snrpd3, Erh, and Snrpd2l might be novel potential therapeutic targets for heart failure." (PMID 37405054, 2023).
multiple myeloma (1 paper, 2021). "In our study, we found for the first time that FASTKD1 and SNRPD3 are related to the prognosis of multiple myeloma, and the specific function and mechanism of these genes in tumorigenesis in multiple myeloma require further study." (PMID 34976013, 2021). "The risk score was also negatively correlated with the expression of immune checkpoints, indicating that ADAR, FASTKD1 and SNRPD3 might interact with the immune microenvironment of multiple myeloma." (PMID 34976013, 2021).
neuroblastoma (1 paper, 2024). Neuroblastoma (NB) is the most common solid, extracranial childhood tumor. "We found that suppression of SNRPD3 caused an increase in the proportion of neuroblastoma cells in the G2/M cell cycle phase resulting in G2/M arrest." (PMID 38049564, 2024). "Our findings highlight that disruption of SNRPD3 protein methylation using PRMT5 inhibitors is a promising novel therapeutic target for the treatment of high-risk neuroblastoma, particularly given the observed SNRPD3- and MYCN-selectivity." (PMID 38049564, 2024). "Given the large number of genes alternatively spliced in high-risk neuroblastoma patients, we next sought to investigate the changes in the splicing landscape resulting from disruptions to MYCN and SNRPD3 expression." (PMID 38049564, 2024). "High mRNA expression of SNRPD3 in human neuroblastoma tissues was a strong, independent prognostic factor for poor patient outcome." (PMID 38049564, 2024). "We found that MYCN up-regulated the expression of the core spliceosomal protein, SNRPD3, in models of neuroblastoma initiation and progression." (PMID 38049564, 2024). "The splicing specificity created by SNRPD3 and MYCN alongside the observed 100% survival in xenografted mice with depleted SNRPD3 expression suggests that neuroblastoma cancer cells are susceptible to therapeutic inhibition of SNRPD3." (PMID 38049564, 2024). "Indeed, the PRMT5 inhibitor, JNJ-64619178, reduced cell viability and SNRPD3 methylation in neuroblastoma cells with high SNRPD3 and MYCN expression." (PMID 38049564, 2024). "We next examined the effects of SNRPD3 on neuroblastoma cell growth in xenograft mouse modelling." (PMID 38049564, 2024). "To investigate whether targeting SNRPD3 methylation is an effective therapeutic strategy in MYCN-amplified neuroblastoma we assessed the effects of the PRMT5 inhibitor, JNJ-64619178 in vitro." (PMID 38049564, 2024). "Indicating that SNRPD3 plays a vital role in neuroblastoma tumorigenesis." (PMID 38049564, 2024). "Importantly, SNRPD3 expression strongly correlated (R = 0.926) with the level of MYC-signature expression during neuroblastoma." (PMID 38049564, 2024). "Indeed, the current study showed that the PRMT5 inhibitor, JNJ-64619178, is effective against neuroblastoma cell lines and demonstrated SNRPD3- and MYCN-dependency." (PMID 38049564, 2024). "As PRMT5 inhibitors affect other protein methylation events, we assessed whether JNJ-64619178 effects on neuroblastoma cell viability were dependent on SNRPD3 in neuroblastoma cells." (PMID 38049564, 2024). "We found that SNRPD3 ensures the fidelity and balance of MYCN-driven alternative splicing events required for neuroblastoma oncogenesis." (PMID 38049564, 2024). "Overall, this study has provided novel insights into the molecular mechanisms of SNRPD3 as an oncogenic protein, and alternative splicing in MYCN-driven neuroblastoma." (PMID 38049564, 2024). "We found that SNRPD3, SNRPF and LSM4 had the strongest independent prognostic effect on neuroblastoma patient outcome among the core spliceosome assembly genes as measured by hazard ratios for event-free (EFS) and overall (OS) patient survival." (PMID 38049564, 2024). "Our findings demonstrate a functional relationship between MYCN and SNRPD3, which maintains the fidelity of MYCN-driven alternative splicing in the narrow range required for neuroblastoma cell growth." (PMID 38049564, 2024). "Here we have determined that a core spliceosome protein, SNRPD3, plays a vital role in maintaining the fidelity and balance of MYCN-driven alternative splicing events which are required to promote neuroblastoma tumorigenesis." (PMID 38049564, 2024). "We hypothesise that a similar mechanism is utilised in neuroblastoma to maintain splicing fidelity, where MYCN increases the expression of PRMT5, SNRPD3, and SNRPD3 methylation." (PMID 38049564, 2024).
neuroblastoma (continued). "Taken together these results indicate that SNRPD3 may have a functional relationship with MYCN and has an important role in neuroblastoma tumorigenesis." (PMID 38049564, 2024). "Together these findings suggest that MYCN, SNRPD3, and PRMT5 proteins may cooperatively complex to enhance SNRPD3 methylation and spliceosome assembly in MYCN-driven neuroblastoma." (PMID 38049564, 2024). "Consequently SNRPD3, MYCN, and PRMT5 expression levels may be used as predictive biomarkers for PRMT5 inhibitor response, not only in neuroblastoma, but potentially other cancers." (PMID 38049564, 2024).
Wilms’ tumour (1 paper, 2024). "This spliceosomal vulnerability likely extends to other components of the spliceosomal machinery such as HNRNPA1, RBM39 and SNRPD3, as well as other cancers such as Wilms’ tumour, where our transcriptomic analyses revealed MYCN regulation of spliceosome regulators including SNRPD1 and WDR77." (PMID 39313128, 2024).
cancer (10 papers, 2017 to 2024). A tumor composed of atypical neoplastic, often pleomorphic cells that invade other tissues. "Our data suggests that cancer-related alternative splicing can be easily disrupted by placing excess demand on the splicing machinery through depletion of SNRPD3, thereby reducing cell viability." (PMID 38049564, 2024). "Overexpression of SNRPD3 has been observed in several cancers but has not yet been linked to childhood cancer." (PMID 38049564, 2024). "The role of SNRPD3 in cancer has really only been discovered in the last decade." (PMID 38049564, 2024). "In addition, depletion of splice factors including SNRPD3, SF3B1, and XAB2 in cancer cells was found to cause defects in sister chromatid cohesion via aberrant splicing of soronin pre‐mRNA." (PMID 28296343, 2017). "However, there have been few study reporting the SNRPD2 and SNRPD3 functions in the cancer." (PMID 35637857, 2022). "SNRPD1, SNRPD3, and SNRPD2 have been identified as spliceosome-related proteins that have previously been crucial in the genesis of cancer." (PMID 36389112, 2022). "Our data adds to the growing body of evidence indicating cell cycle pathways are profoundly affected by SNRPD3 or PRMT5 inhibition, suggesting that combination therapy between PRMT5 and cell cycle inhibitors may be a promising avenue for further exploration in cancer therapeutics." (PMID 38049564, 2024). "Furthermore, the silencing of SNRPD3 (encoding SmD3) in an NSCLC cell line, but not in lung fibroblasts, produced distinct alternative splicing switches in the ADD3 gene from a variant that is associated with cancer progression to a variant predominantly found in non-malignant tissue." (PMID 39684842, 2024).
tumor (6 papers, 2020 to 2025). "It has been suggested that SNRPD3 was associated with the aggressiveness of tumor cells." (PMID 32640634, 2020). "An analysis of the relationships between GRSF1 and tumor stem cell markers revealed significant positive associations with UBE2K, XRCC5, SNRPD3, and CDC123 (Appendix B Figure A2c), which was consistent with previous findings." (PMID 40722682, 2025). "SNRPD3 and U2AF2 showed (50%) the highest association; DDX5, DDX17, and SNRPF in between (40–50%) with neoplasm class." (PMID 34918006, 2022). "However, the SNRPD3 was uncorrelated with the tumor-infiltrating immune cells (all P > 0.05)." (PMID 35637857, 2022).
neurological diseases (1 paper, 2022). "In addition, small nuclear ribonucleoprotein D3 polypeptide (SNRPD3) and PSMB2 are also related to neurological diseases." (PMID 35559016, 2022).
SNRPD3 also shares sentences with these, for which no sentence is quoted: infection (4 papers); mantle cell lymphoma (3); autoimmune disease (2); systemic lupus erythematosus (2); autoimmune disorders (1); bacterial infection (1); dermatomyositis (1); infectious disease (1); infectious mononucleosis (1); polymyositis (1); Sjögren's syndrome (1); spinal muscular atrophy (1); systemic sclerosis (1).